CTSB (cathepsin B)
Diseases named in the same sentence as CTSB in open-access papers (continued):
Sharing a sentence is not in itself a finding about the gene and the disease.
prostate carcinoma (33 papers, 2006 to 2025). A carcinoma that arises from epithelial cells of the prostate gland. "The frequency of these two mutated genes was overall less than 10% in the individual cancer types except for around 12% mutated frequency of CTSB in prostate cancer." (PMID 35155389, 2022). "In prostate cancer, where obesity is associated with a more aggressive phenotype, adipocytes produce cathepsin B (CTSB) upon coculture with prostate cancer cells to support the self-renewal of CSCs." (PMID 28337221, 2017). "Metastasis-associated protein (MTA1) inhibits cathepsin B expression in prostate cancer." (PMID 32727598, 2020). "RD‐N, an aminomethylated derivative of riccardin D, is a lysosomotropic agent that can trigger lysosomal membrane permeabilization followed by cathepsin B (CTSB)‐dependent apoptosis in prostate cancer (PCa) cells, but the underlying mechanisms remain unknown." (PMID 30565390, 2019). "It was suggested that cathepsin B (CTSB) released from the lysosomes after RD‐N treatment triggered apoptosis in prostate cancer (PCa) cells, but the underlying molecular mechanisms responsible for the effects remained unknown." (PMID 30565390, 2019). "DKF is recognized by cathepsin B, a lysosomal protease that is overexpressed in most prostate cancer cells." (PMID 37046671, 2023). "In prostate cancer cells, degradation of ceramide through the action of lysosomal acid ceramidase upregulates Cathepsin-B (CTSB) expression in a S1P-dependent manner." (PMID 37108361, 2023). "CtsB and StfA mRNA and protein distribution were evaluated by in situ hybridization and immunostaining, respectively, in prostate cancer samples." (PMID 35563761, 2022). "RUNX1 knockdown decreased the expression of TMPRSS2 in the human prostate cancer cell line, whereas increased the expression of CTSB/L genes." (PMID 34407143, 2021). "It was suggested that metabolically rich bone microenvironment is responsible for secretion of active CTSB from prostate cancer cells interacting with the bone." (PMID 30027683, 2018). "At the same time, CTSB has been shown to play an important role in invasion and metastasis of prostate cancer." (PMID 30027683, 2018). "Our unpublished data also show induction of CTSB expression in prostate cancer cells, when cocultured with bone cells than when cultured alone." (PMID 30027683, 2018). "In conclusion, our study provides mechanistic and preclinical insight into the critical role of MTA1 in tumor progression and formation of bone metastasis in prostate cancer, at least in part, through the CTSB‐dependent promotion of metastatic pathways." (PMID 30027683, 2018). "Our results offer the MTA1/CTSB axis as a promising target for novel molecular therapies in prostate cancer bone metastasis." (PMID 30027683, 2018). "Increased CTSB expression and activity were observed in bone tissues colonized by human prostate carcinoma cells." (PMID 30027683, 2018). "Of note, MTA1 and CTSB exhibited a strong positive correlation from 69 prostate cancer patient samples (r = 0.38)." (PMID 30027683, 2018). "In conclusion, our present findings show that DMDP-1 induces autophagy and activates calpain-2, while DMDP-2 inhibits autophagy, activates cathepsin B and calpain-2, both leading to caspase-independent cell death in human prostate cancer cells." (PMID 26974436, 2016). "Although no studies have yet reported on COL10A1, ADA, or LHFP and cancer survival, CTSB and MMP9 have both been previously associated with survival in gastric cancer, while ESRRG expression has been associated with survival in prostate cancer." (PMID 23717493, 2013). "TAM expressed cathepsin B or cathepsin S in pancreatic islet, breast or prostate cancer animal models." (PMID 21595995, 2011). "Cathepsin B, a cysteine protease predominantly found in lysosomes, is involved in protein degradation and autophagy and is overexpressed in various cancers such as colorectal, breast, and prostate cancer." (PMID 39274842, 2024).
prostate carcinoma (continued). "Interestingly, it has been shown that TRPV2 expression and functionality in prostate cancer cells increases the expression of MMPs and CTSB." (PMID 34936030, 2021). "In vitro functional studies revealed that Cathepsin B could be secreted into extracellular compartments and that Cathepsin B mediated the effects of ErbB2 and S1p in breast and prostate cancer cell invasion." (PMID 24705283, 2014). "Hence, DMDP-1 & -2 induce CI-PCD in prostate cancer cell lines through calpain-2 and cathepsin B." (PMID 31969640, 2020). "Over-expression of TRPV2 in androgen-dependent LNCaP prostate cancer cells led to the induction of invasive markers, matrix metalloproteinases (MMP9) and cathepsin-B." (PMID 32825277, 2020). "Together, these results demonstrate the critical role of MTA1 as an upstream regulator of CTSB‐mediated events associated with cell invasiveness and raise the possibility that targeting MTA1/CTSB signaling in the tumor may prevent the development of bone metastasis in prostate cancer." (PMID 30027683, 2018). "To explore the clinical significance of the MTA1 and CTSB interrelationship in prostate cancer, we examined the expression of MTA1 and CTSB in a limited cohort of five prostate adenocarcinoma biopsies obtained previously." (PMID 30027683, 2018). "To strengthen our findings from smaller sample numbers, we analyzed the publicly available prostate cancer patient dataset from Oncomine database and found significantly higher levels of both MTA1 and CTSB in tumor samples compared to normal prostate tissues." (PMID 30027683, 2018). "In the presence of adipocytes, prostate cancer cells actively secrete the peptide hormone cholecystokinin (CCK), which not only stimulates prostate CSC self-renewal, but also induces cathepsin B (CTSB) production of the adipocytes." (PMID 26700819, 2016). "In addition, copy number analysis data of the prostate cancer patient samples from independent studies showed an amplification of MTA1 and CTSB." (PMID 30027683, 2018). "We have not investigated the role of cystatin C in modulation of cathepsin B activities in prostate cancer cells, however it is an open possibility considering the similar correlations in other type of tumors." (PMID 19956729, 2009). "In addition, siRNA silencing of TRPV2 reduced the growth and invasion of PC-3 cells in xenograft models of prostate cancer and reduced the expression of invasive markers, MMP2, MMP9, and cathepsin-B, suggesting that inhibition of TRPV2 may reduce the aggressive phenotype of prostate cancer." (PMID 32825277, 2020).
hepatocellular carcinoma (27 papers, 2011 to 2025). A malignant tumor that arises from hepatocytes. "Recent studies have shown that apoptosis triggered by TRAIL in hepatocellular carcinoma cells (Huh-7, Hep3B) was associated with the lysosomal permeabilization and consequently the increase of cathepsin B in the cytosol." (PMID 29996919, 2018). "In hepatocellular carcinoma cells, CTSB was shown to activate the phosphoinositide 3-kinase/Akt pathway, thereby promoting tumor invasion by increasing matrix metallopeptidase 9 expression." (PMID 37768200, 2023). "IGF-1 induces the growth and metastasis of hepatocellular carcinoma by inhibiting protease-induced cathepsin B degradation." (PMID 35203722, 2022). "CD147 promotes hepatocellular carcinoma cells collective invasion via upregulating cathepsin B expression and targeting CD147 would be valuable for the development of novel therapeutic modalities against invasion and metastasis of cancer." (PMID 32727598, 2020). "Upregulated cathepsin B in hepatocellular carcinoma cells facilitated migration and invasion, which mediated CD147-induced invasive phenotype in hepatocellular carcinoma." (PMID 32727598, 2020). "ALDH2, ITGB2, LGALS3, CTSB, PRDX1, and CD14 were identified as multifunctional proteins that are associated with tumorigenesis, damage, cancer cell death, necrosis, fibrosis, hepatocellular carcinoma, steatosis, and inflammation." (PMID 29481576, 2018). "Recently, interaction of HBSP with CTSB was found to promote hepatoma cell motility and invasion, the mechanisms involve the secretion and activation of proteolytic enzymes, increased tumor-induced angiogenesis, and activation of the MAPK/Akt signaling." (PMID 24758376, 2014). "This study was to investigate the effects and safety of cathepsin B-cleavable doxorubicin (DOX)-prodrug (PDOX) for targeting therapy of metastatic human hepatocellular carcinoma (HCC) using DOX as a positive control drug." (PMID 23961994, 2013). "CTSB-mediated scramblase activation triggers cytotoxicity and cell cycle arrest by andrographolide to overcome cellular resistance in cisplatin-resistant human hepatocellular carcinoma HepG2 cells." (PMID 37576397, 2023). "CTSB and its endogenous inhibitors may promote proteolysis in hepatoma cells, thereby contributing to the invasive phenotype of this cancer." (PMID 37576397, 2023). "Despite CTSB potentially being involved in both normal and pathological functions, there are well-established roles in carcinogenesis (hepatocellular carcinomas, colon cancer, esophageal adenocarcinoma, pancreatic adenocarcinoma, cellular functions apoptosis, oxidative stress, and autophagy)." (PMID 34769258, 2021). "Furthermore, we found that elevated expression of CD147 as well as cathepsin B were correlated with poor prognosis in patients with hepatocellular carcinoma." (PMID 32727598, 2020). "Indeed, the cytosolic cathepsin B/L activity as well as the LDH release were also abolished by IRGM1 siRNA in IFN-γ/Con A-treated hepatoma cells." (PMID 22163006, 2011). "In hepatocellular carcinoma, the phosphorylation of Akt in CTSB-overexpressing cells was significantly increased, which may also indicate that CTSB regulates the progression of HCC through the PI3K/Akt signaling pathway." (PMID 37576397, 2023). "Enolase 1 (ENO1) and cathepsin B (CTSB), found in both LUSC-PGS and GBM-PGS, are predictive biomarkers for hepatocellular carcinoma, gastric cancer, or oral squamous cell carcinoma." (PMID 33277589, 2020). "However, the role of CTSB in hepatocellular carcinoma (HCC) progression remains unclear." (PMID 26896959, 2016). "Overexpression of CTSZ/X in hepatocellular cancer enhances motility and invasion via inhibition of E-cadherin and induction of fibronectin, while secretion of CTSB and CTSL was promoted by Abl/Arg nonreceptor tyrosine kinases in melanoma cell lines." (PMID 33809973, 2021).
hepatocellular carcinoma (continued). "Furthermore, CTSX is upregulated in metastatic gastric cancer, enhanced levels of CTSB and CTSL accompany malignant ovarian tumors, and CTSS directly supports invasion of hepatocellular carcinoma cell lines." (PMID 27802179, 2016). "Concomitant with inhibiting cathepsin B and increasing p62 levels, bortezomib also stimulated ERK phosphorylation in ovarian cancer cells, endometrial cancer Ishikawa cells, and hepatocellular carcinoma HepG2 cells." (PMID 25375375, 2014). "Indeed, in the hepatocellular carcinoma cell line HepG2, MEN1-KD did not inhibit the transcription of lysosomal and autophagic genes such as CTSB and SQSTM1." (PMID 40057469, 2025).
gastric cancer (26 papers, 2007 to 2025). A primary or metastatic malignant neoplasm involving the stomach. "The increased expression of cathepsin B is associated with more aggressive potential and plays a role in gastric cancer invasion, so it may be a promising target in anticancer treatment." (PMID 34770912, 2021). "For example, miR-185-3p directly targets CTSD in gastric cancer, and miR-3619 targets both CTSB and CTSD in their 3′ UTR sequence to negatively regulate their expression." (PMID 38611021, 2024). "It was found that the increased cell apoptosis in gastric cancer leads to the release and degradation of CTSB protein from the lysosome, resulting in gastric cancer cell death." (PMID 36311733, 2022). "The higher levels of cathepsin B are also demonstrated in the urine and serum from patients with gastric carcinoma." (PMID 34770912, 2021). "The LC3 puncta largely colocalized with cathepsin B immunoreactivity in poorly differentiated human gastric carcinomas, indicating that gastric adenocarcinomas undergo both stages of the autophagy/lysosome process." (PMID 24527069, 2014). "in his research has reported increased expression of Cathepsin B in gastric carcinoma as compared to normal tissue which is found to be significantly associated with tumor size (p < 0.001), Tumor Node Metastasis (TNM) stage (p < 0.001) and decreased overall survival (p < 0.001)." (PMID 35260133, 2022). "PGC expression suppressed the proliferation, anti-apoptosis, migration and invasion of gastric cancer cells possibly by interaction with CCNT1, CNDP2 and CTSB." (PMID 37291517, 2023). "PGC expression suppressed the proliferation and invasion of gastric cancer cells possibly by interacting with CCNT1, CNDP2 and CTSB." (PMID 37291517, 2023). "Its expression level in CTSB+ and CD68 + macrophage could act as an indicator for early warning of primary gastric cancer." (PMID 36333291, 2022). "CTSB and CTSL were reported to be elevated in gastric carcinoma and correlated with its malignant property, but specific expression of neither CTSB or CTSL in sig-type GC-derived cell lines could be detected." (PMID 23451082, 2013).
pancreatitis (25 papers, 2008 to 2026). Inflammation of the pancreas. "Sendler M and Fortunato F also found an association between high expression of CTSB and increased severity of pancreatitis." (PMID 35872750, 2022). "So far, CTSB mutations have been studied in pancreatitis and neurodegenerative disorders, but little is known about the structural and functional effect of variants in CTSB." (PMID 31592339, 2019). "Furthermore, the mouse model would be important conceptually, as the exact role for CTSB in pancreatitis cannot be convincingly ascertained by the phenotype of the CTSB-deficient mice." (PMID 31235832, 2019). "Thus, CTSB deficiency can affect multiple aspects of the pancreatitis response and the final phenotypic outcome may be mechanistically misleading." (PMID 31235832, 2019). "In the initial stage of experimental AP, CTSB plays a major role in pathological trypsinogen activation in the early course of cerulein-induced pancreatitis." (PMID 41277866, 2026). "Cathepsin B (CTSB) plays a key role in early trypsinogen activation during the onset of pancreatitis." (PMID 41530118, 2026). "Here, the authors show that cystatin C (CST3) regulates the activity of cathepsin B during pancreatitis in a pH dependent manner." (PMID 39962054, 2025). "By necessity, the CST3-mediated inhibition of CTSB needs to be overcome for CTSB to activate trypsinogen during pancreatitis." (PMID 39962054, 2025). "Enzyme activity measurements within the subcellular fractions showed that the majority of CTSB activity is localised to the lysosomal compartment in untreated controls but redistributed into the zymogen granule fraction 1 h after onset of pancreatitis." (PMID 39962054, 2025). "When comparing the pancreatitis against the healthy control group, arginase, cathepsin B, MMP1, −3, −9, and neutrophil, elastase demonstrated to have significant differences in measured fluorescence signal." (PMID 40292193, 2024). "Next Generation Sequencing was performed to analyze a panel of nine genes associated with pancreatitis (CaSR, CFTR, CPA1, CTRC, CTSB, KRT8, PRSS1, PRSS2, and SPINK1)." (PMID 38927485, 2024). "CTSB, CTSL, and CTSS are known to be up-regulated in pancreatitis, and although the roles of CTSB and CTSL are well-established that of CTSS is less known." (PMID 35183119, 2022). "Lysosomal dysfunction in pancreatitis is indicated by the findings that the maturation of cathepsin B and cathepsin L are reduced and that autophagosome formation is increased while lysosomal degradation is decreased." (PMID 33990205, 2021). "As a first step towards a CTSB-dependent mouse pancreatitis model, here we performed biochemical studies to identify T7 trypsinogen mutants that cannot autoactivate but are selectively and robustly activated by CTSB." (PMID 31235832, 2019). "Ideally, a CTSB-dependent preclinical pancreatitis model can be created, which will be useful for testing therapeutic approaches targeting CTSB." (PMID 31235832, 2019). "To address this problem, we set out to generate mouse models in which the two trypsinogen activation processes (autoactivation versus CTSB-mediated activation) can be experimentally separated and their effect on pancreatitis studied selectively." (PMID 31235832, 2019). "Edema is often a major complication of TBI and compounds, which inhibit cathepsin B, reduced edema in ischemic and pancreatitis models." (PMID 26388830, 2015). "Previous studies have suggested that intrapancreatic activation of trypsinogen contributes to pancreatitis and is, in part, mediated by the activity of cathepsin B (CTSB)." (PMID 22132114, 2011). "To find out in which subcellular compartment this increased activity was located we prepared subcellular fractions of pancreatic tissue from control and 1 h pancreatitis animals and measured enzyme activities of CTSB, CTSL, trypsin, and chymotrypsin in these subcellular fractions." (PMID 39962054, 2025).